HK1 (hexokinase 1)
Diseases named in the same sentence as HK1 in open-access papers (continued):
Sharing a sentence is not in itself a finding about the gene and the disease.
Myocardial fibrosis (1 paper, 2023). "In this work, we confirmed that chicoric acid inhibits isoproterenol‐induced myocardial fibrosis by regulating the HK1/NLRP3 inflammasome pathway, thereby inhibiting inflammation, oxidative stress, and apoptosis." (PMID 38268894, 2023).
nonalcoholic fatty liver disease (1 paper, 2023). "More importantly, we find thatlncRP11-675F6.3 and HK1 attenuate high fat diet induced nonalcoholic fatty liver disease (NAFLD) by regulating VLDL-related proteins and autophagy." (PMID 37222534, 2023).
oncocytomas (1 paper, 2021). "Interestingly, our results showed that HK1 was positive in most oncocytomas, but negative in other renal neoplasms." (PMID 34482820, 2021).
papillary thyroid carcinoma (1 paper, 2026). "Notably, we identified a protein interaction between TGM2 and HK1 that was significantly upregulated in the papillary thyroid carcinoma cell line TPC-1." (PMID 41571643, 2026).
preeclampsia (1 paper, 2017). Preeclampsia is a hypertensive disorder of pregnancy that is characterized by new-onset hypertension with proteinuria presenting after 20 weeks of gestation, and depending on mild or severe forms may initially present with severe headache, visual disturbances, and hyperreflexia. "In late-onset preeclampsia, expression levels of essential mitochondria-related proteins VDAC1, TFAM, hexokinase 1, PGC-1α and PGC-1β, and autophagy marker LC3A, were significantly elevated." (PMID 28736722, 2017).
PURA syndrome (1 paper, 2025). "Additionally, two chronic neurodevelopmental disorders, HK1 Variants and PURA (also referred to as Pur-alpha) syndrome, have been reported to present with low CSF glucose in some patients (HK1 variants) or potentially in most patients (PURA syndrome)." (PMID 39745620, 2025).
rectal cancer (1 paper, 2020). A primary or metastatic malignant neoplasm that affects the rectum. "LncARSR-miR-34a-5p-HK1 axis (HK is another glycolytic limiting enzyme) facilitates the progression of rectal cancer by promoting glycolysis metabolism." (PMID 33287763, 2020).
renal angiomyolipoma (1 paper, 2023). "After applying Pearson analysis, we identified five proteins (out of the 34 intersected DE proteins) positively correlated with the maximum renal angiomyolipoma (p < 0.05), namely, PCSK1N, PMEL, HK1, GOT2 and SPTBN2." (PMID 36891236, 2023).
Renal neoplasm (1 paper, 2021). The presence of a neoplasm of the kidney. "By setting a cutoff score above 2 and > 90% cell positivity, HK1 has a sensitivity of 96.7% as a biomarker with a specificity of 98.7% in distinguishing ROs from other renal neoplasms." (PMID 34482820, 2021).
sarcoma (1 paper, 2021). A usually aggressive malignant neoplasm of the soft tissue or bone. "On the one hand, the transcriptomic profile of invasive sarcoma cells revealed increased expression of both hexokinase-1 (Hk-1) and phosphofructokinase-P (Pfk-p), two important enzymes of glycolytic pathway, in good agreement with their extra glycolytic proficiency." (PMID 34070472, 2021).
serous ovarian carcinomas (1 paper, 2021). "Correspondingly, in primary cancer cells cultivated from high-grade serous ovarian carcinomas, the levels of HK1 and HK2 correlated at the mRNA and protein levels." (PMID 34895333, 2021).
sideroblastic anemia (1 paper, 2021). "The remaining new variants were identified in enzyme genes (PKLR: p.R531S; HK1: p.R12X, p.G451R; NT5C3A: p.R22X), and in genes associated with sitosterolemia (ABCG5: p.Y458X) and sideroblastic anemia (ALAS2: p.H524R)." (PMID 34093240, 2021).
spina bifida (1 paper, 2020). A congenital neural tube defect in which vertebrae are not fully formed. "However, polymorphisms within Hk1 have been linked to human spina bifida in Chile." (PMID 33066028, 2020).
squamous carcinoma (1 paper, 2018). "In the squamous carcinoma cell line SCC-9, ATF2 translocates to the mitochondria following genotoxic stress and disrupts the Hexokinase 1 (HK1)—Voltage dependent anion channel 1 (VDAC1) complex, thereby compromising mitochondrial membrane pore permeability and promoting apoptosis." (PMID 30497386, 2018).
type 1 diabetes (1 paper, 2022). "In another study, using Western blotting, it was shown that, in human islets with type 1 diabetes, GCK and HK1/2 are activated, facilitating the flow of glucose through glycolysis." (PMID 36430204, 2022).
cancer (320 papers, 2009 to 2026). A tumor composed of atypical neoplastic, often pleomorphic cells that invade other tissues. "HK1 is overexpressed in a series of cancers, including PC, and elevated HK1 levels are associated with poor prognosis in PC." (PMID 37892195, 2023). "HK1 is associated with cancer progression, promotes cell proliferation, and is expressed in several cancer types." (PMID 37922300, 2023). "It plays a role in the progression of cancer via its association with hexokinase 1 (HK1) and hexokinase 2 (HK2) in aerobic glycolytic cancers." (PMID 32327997, 2020). "Among the PRCa genes expressed at the protein level are transcriptional regulators (Hdac2 and Hmga2), cancer-linked genes (Klf4 and Kit), and genes involved in glycolysis and pyruvate metabolism (Hk1, Eno2, and Pck2)." (PMID 22305566, 2012). "Together, HK1 silencing not only induced a switch in energy metabolism from aerobic respiration to glycolysis, but also caused tumor malignancy, including increased cancer cell proliferation and metastasis." (PMID 29721175, 2018). "Few studies have demonstrated that HK1 is associated with therapeutic effectiveness against cancer." (PMID 26576639, 2015). "In this regard, studying the modulatory effects of miRNAs and lncRNAs on those glycolytic proteins linked with cancer progression, e.g., HK1, GAPDH, PKM2, GLUT1, GLUT3, HIF-1α, CAV1, Ras, HK2, LDHA, PGI/AMF, and PFKFB3, might be very favorable for the design of novel treatments for PC." (PMID 36332600, 2023). "In the context of cancer, the authors showed that Src-stimulated tumorigenesis and metastasis was dependent on HK activity using different approaches, such as mutations in Src phosphorylation site of either HK1 or HK2 and hexokinase silencing in xenograft mouse models." (PMID 36217026, 2022). "Notably, genes associated with the glycolysis/gluconeogenesis pathway including LDHA —whose overexpression in cancer is associated with proliferation and malignancy— and several glycolytic genes (e.g. HK1, VDAC1, and VDAC2) were only upregulated in LB fHER2− tumours and derived CLs." (PMID 36220861, 2022). "On the contrary, increased protein and mRNA levels of LDHA, PGK1, and HK1 were detected in cancer cells cultured at different concentrations of NaLac." (PMID 40849487, 2025). "Among them, HK2 isoenzyme was found to be overexpressed in various cancer types, while HK1 is the predominant isoform in normal cells." (PMID 40941984, 2025). "In summary, our study uncovers a novel mechanism that NPPS boosts glycolysis and promotes cell proliferation in RAS-mutant cancers through its interaction with HK1, a rate-limiting enzyme in glycolysis." (PMID 39506063, 2025). "We demonstrated that NR6A1 plays an oncogenic role, that it activates p-mTOR, and increases the levels of HK1 in these cancer cells." (PMID 41219936, 2025). "To further assess the role of intracellular fructose production in oncogenic glycolysis, we generated cancer cells with impaired glucose metabolism by deleting both HK1 and HK2." (PMID 39406918, 2024). "Much of the interest in HKDC1’s role in cancer stems from the fact that, like HK1 and 2, it localizes in the mitochondrial outer membrane (MOM) and binds with the voltage-dependent anion channel (VDAC)." (PMID 37109475, 2023). "KRAS4A can interact with Hexokinase 1 and relieve glucose-6-phosphate-dependent allosteric inhibition of Hexokinase 143 possibly enabling Hexokinase 1 to be a stronger driver of glucose consumption than Hexokinase 2 in certain cancers." (PMID 36697489, 2023). "Hexokinase 1: The expression of HK1 is amplified in some cancers where it is responsible for rewiring the metabolic state towards aerobic glycolysis to supply ATP and macromolecules." (PMID 37109475, 2023). "This allows it to bind to heterokinase HK1 on the outer mitochondrial membrane and stimulate HK1 activity, thereby increasing glycolysis in cancer cells." (PMID 37296881, 2023).
cancer (continued). "We corroborated these findings by validating the expression of their key candidate markers: HK1, which regulates glycolysis, and the E2F2 transcription factor associated with key cancer pathways." (PMID 35626705, 2022). "Cancer-associated fibroblasts (CAFs), which mainly derived from HSCs in HCC, also secreted more HK1 than quiescent HSCs (right)." (PMID 36192599, 2022). "The challenge lies in the development of HK2 inhibitors that target cancer but induce limited interference with the ubiquitously expressed HK1 isozyme." (PMID 33187984, 2021). "HK-2 was found to be overexpressed more than HK-1 in several cancer types compared with their normal counterpart." (PMID 32372141, 2020). "Since hexokinase serves as the gateway through which glucose enters the alternative metabolic pathway, HK-1 is redundant to the primary catalytic role of HK-2 to ensure the cancer cell a constant glycolytic flux." (PMID 32372141, 2020). "In a study, recently published inNature,titled “KRAS4A directly regulates hexokinase 1”, Amendola et al14reported a direct and unique interaction between KRAS4A and hexokinase 1 (HK1) in cancer cells." (PMID 32879916, 2020). "A doxycycline-inducible shRNA silencing system was used to examine the effect of HK2 knockdown in cultured cells and in xenograft models of HK1−HK2+ and HK1+HK2+ cancers." (PMID 29988332, 2018). "Taken together, these results demonstrate that HK1 knockdown accelerates tumor malignancy, including increased cancer cell proliferation and metastasis." (PMID 29721175, 2018). "HK2 becomes overexpressed in many cancer types, either in conjunction or instead of the normal HK1 isozyme, where it binds to the outer mitochondrial membrane via the VDAC1 channel." (PMID 30400835, 2018). "Usually, HK2 is regarded as a principle enzyme in cancer metabolism; however, our study suggests that HK1 is the main enzyme converting glucose to glucose-6-phosphate in SPNs." (PMID 29552289, 2018). "The results revealed that most cancer types exhibit low to moderate levels of the HK1 protein but display moderate to high levels of HK2 protein (data not shown)." (PMID 29721175, 2018). "This is consistent with our prior data comparing mouse brain and human cancer cell lines, which also suggested that HK1 is the major hexokinase in the brain." (PMID 28962651, 2017). "Overexpression of HK1 in tumors seems to be the mechanism for the protection of cancer cells against oxidative stress and apoptosis, as well." (PMID 28105937, 2016). "Of the many subtypes of glucose transporters and hexokinases, the GLUT1 subtype is considered to be the glucose transporter mainly upregulated in cancer cells and HK1 and HK2 are the hexokinase subtypes most frequently found overexpressed in cancer cells." (PMID 26824929, 2013). "For example, silencing the hexokinase 1 (TbHK1) gene in T. brucei induced parasite death, and a similar effect has been observed using the hexokinase inhibitor lonidamine, both in cancer and trypanosome cells." (PMID 25937964, 2013). "This is consistent with the established biology wherein HK1 is the predominant isoform responsible for pathological stress responses in differentiated tissues, while HK2 is more frequently associated with proliferative states such as cancer." (PMID 41503885, 2025). "overexpression of HK-1 and HK-2 likewise has pro-cancer effects." (PMID 40165895, 2025). "HK1 participates in distinct biological processes contributing to glycolysis in cancer." (PMID 36781976, 2023). "JunB and C/EBPβ are transcription factors that activate genes involved in glycolysis, such as PFKP, PGAM1, and HK1, thereby promoting glycolysis in cancer cells and limiting the activation and effector states of CD8+ T cells, promoting tumorigenesis and progression." (PMID 37582735, 2023).
cancer (continued). "This may be due to the fact that HK2, instead of HK1, is frequently upregulated in cancer, and, in addition, the binding of HK2 to the external mitochondrial membrane in a complex with VDAC1 is known to contribute to fuel the glycolytic process." (PMID 34557403, 2021). "Cancer cells exhibit high glycolytic activity during rapid proliferation even in the presence of normal oxygen concentrations in culture; therefore, we examined changes in doubling times following the HK1 and HK2 deletions." (PMID 34895333, 2021). "Yet, further investigations are needed to reveal whether PARP-1-dependent effects on glycolytic activity of irradiated cancer cells are also due to inhibition of HK-1." (PMID 34825138, 2021). "Tseng and colleagues reported that HK1 silencing induces a switch in energy metabolism specifically from oxidative phosphorylation to aerobic glycolysis and enhances tumor malignancy, increasing cancer cell proliferation and metastasis." (PMID 34557403, 2021). "They found that KRAS4A can directly bind to HK1 in mitochondria, thereby blocking the allosteric inhibition of HK1 which could lead to enhanced glycolytic flux in cancer cells." (PMID 32879916, 2020). "Because cancer cells must transfer glucose into the pentose phosphate pathway to maintain their rapid growth, blocking the direct regulation of HK1 by KRAS4A is a potentially effective method for treating cancer, especially for tumors with high oncogenic KRAS4A expression." (PMID 32879916, 2020). "Surprisingly, differential HK1 level could better stratify cancer-specific survival rates than HK2 in HNSCC patients, suggesting that HK1 and HK2 might play differential roles during HNSCC tumorigenesis." (PMID 32195170, 2020). "In addition, HK2 is expressed in a wide range of cancers, from tissues that normally express only HK1." (PMID 29988332, 2018). "Consequently, HK2 knockdown by DOX-induced shHK2 resulted in a greater reduction of both glucose consumption and lactate production more pronounced in HK1−HK2+ cancer cells (Hep3B, Huh7) compared to HK1+HK2+ cancer cells (SUM159)." (PMID 29988332, 2018). "Future studies in regulation of HK1 expression in cancers and in normal tissues may provide targets for combination therapies in conjunction with HK2 inhibition for cancer treatment." (PMID 29988332, 2018). "In contrast, there was no significant synthetic lethality induced by the triple combination of shHK2/DPI/PER in HK1+HK2+ cancer cells, suggesting that our shHK2/DPI/PER triple-combination treatment is selectively cytotoxic for HK1−HK2+ cancer cells and is likely to be tolerated by normal tissues." (PMID 29988332, 2018). "In addition, to further assess the effect of HK1 knockdown on cancer cell growth, colony formation and soft agar clonogenic assays were carried out." (PMID 29721175, 2018). "Since the EMT phenotype induced by HK1 knockdown might enhance cancer cell migration and invasion, these behaviours were examined." (PMID 29721175, 2018). "Herein, we clearly show that ATF2 can interact with VDAC1 to disrupt the HK1/VDAC complex in various cancer cells, suggesting that ATF2 might bind to VDAC1 in competing with HK1 and thus promote cytochrome c release." (PMID 25852302, 2015). "Differential interactions of HK1 and HK2 with mitochondria may underlie different glycolytic profiles in cancer cells." (PMID 24648844, 2014). "However, like HK1+ cells/tissues, HK1+HK2+ cancers are not susceptible to this therapy, despite the reduction in their HK2-driven glycolytic activity." (PMID 29988332, 2018). "Moreover, HK1 expression is much higher in metastatic colon cancers than in primary cancers." (PMID 28054552, 2017). "In general, the associations between Carbon Metabolism and Pathway in Cancer genes become weaken in HCC, whereas the associations between a number of genes are enhanced, especially those in the 22 up-regulated carbon metabolism genes group (such as HK1, PGK1, ENO1, PGLS, RPE)." (PMID 27363021, 2016).